S100A9 (S100 calcium binding protein A9)
Diseases named in the same sentence as S100A9 in open-access papers (continued):
Sharing a sentence is not in itself a finding about the gene and the disease.
ischemic stroke (5 papers, 2021 to 2025). A stroke disorder caused by obstruction of blood flow to the brain, due to thrombotic (local blood clot formation) or embolic (due to a blood clot or other material traveling from another site) event. "S100A9 is associated with adverse outcomes in patients with ischemic stroke (IS)." (PMID 40661125, 2025). "However, after ischemic stroke, the proportion of ‘classical’ monocytes that were S100A9‐positive significantly increased and was associated with poor outcomes in patients with AIS." (PMID 39107960, 2024). "Furthermore, we have studied the composition of ischemic stroke thrombi and characterized S100A9 content, to assess its association with thrombus components and clinical parameters." (PMID 33402185, 2021). "Our current research findings reveal that S100A9‐mediated M/M polarization exacerbates neuroinflammatory injury through the STAT6/PPARγ pathway in ischemic stroke." (PMID 39107960, 2024). "We performed in vivo experiments to investigate the role of S100A9 in the pathology of ischemic stroke." (PMID 39107960, 2024). "Second, we only focused on the function of S100A9 in M/M in ischemic stroke since these cells undergo specialized phagocytosis in the brain." (PMID 39107960, 2024). "One clinical study has shown that S100A9 represents a reliable biomarker in distinguishing acute progressive ischemic stroke from acute non‐progressive ischemic stroke, thus suggesting its potential role in ischemic pathophysiology." (PMID 39107960, 2024). "Our study elucidated that the neuroprotective effect of S100A9 disabling in ischemic stroke can be attributed to facilitating the shift of the M/M anti‐inflammatory phenotype and the efficiency of efferocytosis." (PMID 39107960, 2024). "The disruption of S100A9 in M/M ameliorates brain injury through the STAT6/PPARγ pathway in ischemic stroke." (PMID 39107960, 2024). "Our histological analysis showed that S100A9 is present in all ischemic stroke thrombi and correlated with inflammatory cells and platelets." (PMID 33402185, 2021). "Immunization with an anti-S100A9 vaccine in a mouse ischemic stroke inhibited long-term thrombus formation, through inhibition of increased S100A9/CD36 signaling, without risk of bleeding or adverse autoimmune responses." (PMID 34239729, 2021). "Moreover, our research has identified that S100A9‐mediated M/M polarization aggravates neuroinflammatory injury via the STAT6/PPARγ pathway in ischemic stroke, providing a new understanding of the molecular mechanisms involved." (PMID 39107960, 2024). "Furthermore, a study developed a vaccine against S100A9 that inhibited thrombosis without increasing the risk of bleeding in ischemic stroke in mice." (PMID 39107960, 2024). "In addition, targeting S100A9 by therapeutic vaccine inhibits thrombosis without increasing the risk of bleeding in ischemic stroke mice." (PMID 39107960, 2024). "However, the expression of S100A9 in monocytes and its correlation with the prognosis of ischemic stroke is unknown." (PMID 39107960, 2024). "Therefore, S100A9 may harm ischemic stroke outcomes, and its function may be cell‐targeted." (PMID 39107960, 2024). "Notably, S100A9 blockade by PQD may be a promising therapeutic intervention in mitigating brain injury and promoting favorable outcomes after ischemic stroke." (PMID 39107960, 2024).
kidney stones (5 papers, 2013 to 2023). "To further study the role of S100A8 and S100A9 in nephrolithiasis, we think two important questions should be addressed first." (PMID 37051106, 2023). "M1-polarized macrophages were the predominant cell type expressing S100A8 and S100A9 in the kidneys of nephrolithiasis patients." (PMID 37051106, 2023). "With the development of mass spectrometry, proteomic studies have frequently identified calgranulins S100A8 and S100A9 in the kidney stone matrix." (PMID 37051106, 2023). "Renal sources and important regulators for S100A8 and S100A9 in nephrolithiasis were explored in this study." (PMID 37051106, 2023). "In this study, the expression of S100A8 and S100A9 in renal tissue was also found to be elevated in kidney stone patients." (PMID 34395096, 2021). "It is unclear whether S100A8 and S100A9 from M1-polarized macrophages play proinflammatory and lithogenic roles in nephrolithiasis." (PMID 37051106, 2023). "However, S100A8 and S100A9 were mainly expressed in the renal interstitium of kidney stone patients." (PMID 34395096, 2021). "Therefore, we could make a reasonable conclusion that renal-up-regulated S100A8 and S100A9 in kidney stone patients are predominantly derived from macrophages of M1 type." (PMID 37051106, 2023). "Certainly, the decrease of kidney stones itself reduces renal cell injury, and thus, may reduce the production of DAMPs, as evident by the reduction of S100A9 in the kidney at a certain level even by rOPN, pAA5.1, or D9E3 peptide, which are impotent to remove DAMPs." (PMID 35922481, 2022). "In addition, S100A8 and S100A9 were detected in the renal interstitium of kidney stone patients, which may originate from macrophages in the kidney." (PMID 34395096, 2021). "However, how S100A8 and S100A9 participate in kidney stone formation is unknown." (PMID 37051106, 2023). "Our previous study demonstrated that urinary exosomes from kidney stone patients were rich in S100A8 and S100A9." (PMID 34395096, 2021). "Immunohistochemistry results showed that the expression of S100A8, S100A9 and OPN was significantly increased in renal tissue from kidney stone patients." (PMID 34395096, 2021). "In addition to analyses of human fluids and kidney stones, cell culture studies have revealed various PTMs on S100A8 and S100A9." (PMID 36826733, 2023).
leishmaniasis (5 papers, 2013 to 2024). Infectious disease that is transmitted through the bite of hematophagous female phlebotomine sand flies. "Furthermore, S100A8/S100A9 can act as a very early and sensitive biomarker in experimental leishmaniasis for phagocyte activation linked to an effective Th1-response." (PMID 25098555, 2014).
metastatic melanoma (5 papers, 2010 to 2022). A melanoma that has spread from its primary site to another anatomic site. "Increased expression of the two downstream regulators of ID1, S100A8 and S100A9 levels was also observed (1.8- and 1.7-fold higher and up to 3.1- and 2.7-fold, respectively) in CD11B+ PBMCs from patients with metastatic melanoma compared with healthy, age-matched controls (unpaired t-test, P<0.01)." (PMID 25924227, 2015).
nasopharyngeal carcinoma (5 papers, 2017 to 2024). A carcinoma arising from the nasopharyngeal epithelium. "The overexpression of S100A9 is positively correlated with paclitaxel resistance in nasopharyngeal carcinoma." (PMID 39451208, 2024). "Recently, more and more findings suggest that S100A9 is up-regulated in numerous cancer types, and its levels are also increased in the stroma of nasopharyngeal carcinoma." (PMID 28355254, 2017). "In addition, pacritinib has also been reported to reduce chemotherapy resistance in nasopharyngeal carcinoma, mainly by regulating the phosphorylation level of IRAK1, thereby inhibiting the expression of S100A9 and reducing the patients with nasopharyngeal carcinoma resistance to paclitaxel." (PMID 35669566, 2022).
Peripheral Artery Disease (5 papers, 2015 to 2025). "In human studies, the two calprotectin subunits S100A8 and S100A9 were detected in atherosclerotic plaques and elevated in serum of patients suffering from peripheral artery disease." (PMID 26663990, 2015). "The pathways associated with neutrophil activation, chemotaxis, and migration were significantly correlated with the high expression of S100A8, S100A9, S100A12, and CXCR2 in CD and peripheral arterial disease." (PMID 40422241, 2025). "Based on the results from selecting hub genes among 15 potential candidate genes, four hub genes were selected that were significantly upregulated in both CD and peripheral arterial disease: S100A8, S100A9, S100A12, and CXCR2." (PMID 40422241, 2025).
prostate tumors (5 papers, 2012 to 2021). "High S100A9 in prostate tumors is also associated with biochemical recurrence." (PMID 34067757, 2021). "Also, S100A9 expression was observed in association with CD68+ macrophages in biopsies from human prostate tumors." (PMID 22470535, 2012). "In experimental models, depletion of extratumoral macrophages/monocytes and decreased S100A9 expression inhibited prostate tumor growth." (PMID 34067757, 2021). "The expression of S100A9 was related to the expression of CD68 macrophages in a human prostate tumor biopsy." (PMID 33912559, 2021). "In patients, S100A9 is upregulated in aggressive prostate tumors and in the rest of the tumor-bearing prostate." (PMID 28472073, 2017). "Particularly as human prostate tumors contain numerous S100A9 expressing inflammatory cells and also some S100A9 expressing tumor epithelial cells, and the overall effect of infiltrating monocytes is to stimulate prostate tumor growth." (PMID 22470535, 2012). "Also in human prostate tumors there was S100A9 expression which coincided with infiltrating macrophage-like inflammatory cells in the tumor stroma." (PMID 22470535, 2012). "We have previously shown that S100A9 expression is detected in CD68 positive macrophages in the prostate tumor stroma and in the non-malignant prostate stroma adjacent to prostate tumors, suggesting monocytes/macrophages as a plausible source of S100A9 also in tumors." (PMID 34067757, 2021).
schizophrenia (5 papers, 2012 to 2025). A major psychotic disorder characterized by abnormalities in the perception or expression of reality. "The highlight of this study was the identification of four key genes associated with schizophrenia: significant upregulation ofS100A8, S100A9 and BCL2A1 and downregulation of CBLB." (PMID 40162448, 2024). "Our study did not confirm differential expression of CXCL1, but of the other 6 genes, S100A9 (under-expressed in schizophrenia) was found in the Yellow module, one of the modules that is negatively associated to schizophrenia in the medicated dataset." (PMID 22761806, 2012). "Our study confirms the upregulation of S100A8 and S100A9 in schizophrenia, which has been well-documented in previous research." (PMID 40162448, 2024). "The upregulation of S100A8 and S100A9 aligns with the role of calprotectin, aheterodimeric protein complex involved in neuroinflammation, in schizophrenia." (PMID 40162448, 2024). "In summary, S100A9 may play an important role in immune regulation of schizophrenia through its interaction with multiple immune cells." (PMID 40980038, 2025). "This study identified key molecular changes in schizophrenia, notably the upregulation of S100A8, S100A9 and BCL2A1 and thedownregulation of CBLB, highlighting the involvement of neuro-inflammatory pathways, apoptosis regulation and immune modulation in thedisease." (PMID 40162448, 2024). "Additionally, the potential of S100A8, S100A9 and EGF as biomarkersfor disease severity and treatment response opens new possibilities for personalized therapeutic approaches in managing schizophrenia." (PMID 40162448, 2024). "Inflammation related genes including S100A8, S100A9 and CHI3L1 are elevated in the hippocampus in schizophrenia and perivascular macrophages (CD163+) have been identified in the lumen of blood vessels and surrounding the endothelial cells in at least one schizophrenia hippocampus." (PMID 30214039, 2020).
thyroid cancer (5 papers, 2012 to 2026). "The damage-associated molecular pattern proteins, S100A8 and S100A9, enhanced growth and invasiveness of various cancer cell lines and are implicated in liver, brain, breast, colon, thymus and thyroid cancers." (PMID 34517344, 2021). "It has been previously reported that the S100 proteins S100A2, S100A4, S100A6, and S100A9 are upregulated in thyroid cancer and that these subfamily members are involved in the progression of cancer in different ways." (PMID 32015423, 2020). "In thyroid carcinoma, expression of S100A8 and S100A9 in cancer cells is crucial for dedifferentiation." (PMID 22838504, 2012).
triple-negative breast carcinoma (5 papers, 2020 to 2022). An invasive breast carcinoma which is negative for expression of estrogen receptor (ER), progesterone receptor (PR), and human epidermal growth factor receptor 2 (HER2). "In addition, BAP18 has been also implicated in triple-negative breast cancer development through the activation of the oncogene S100A9." (PMID 36142452, 2022). "To investigate the prophylactic effect of S100A9‐targeted CPMV in a murine triple negative breast cancer (TNBC) model, we first exposed Balb/C mice to CPMV or S100A9‐targeted CPMV via i.v. injection, and then challenged mice with luciferase‐labeled 4T1 (4T1‐Luc) cells." (PMID 34519180, 2021).
acne (4 papers, 2014 to 2025). An inflammatory process of the sebaceous glands which is characterized by comedones, nodules, papules and/or pustules on the skin. "The expression of AMPs human cathelicidin antimicrobial protein (hCAP18), lipocalin (LCN2), human beta-defensin 2 (hBD2), hBD3, S100A7 and S100A9 were found significantly upregulated in acne lesions in the Finnish patient group by RT-PCR." (PMID 25153527, 2014). "Using a murine/human aGVHD gene signature we identified a cluster of ITGAX+CD14+S100A9+PTGS2+ macrophages that expanded in psoriatic but not acne skin compared with healthy controls." (PMID 35584681, 2022).
allergies (4 papers, 2014 to 2022). "The genes S100A8 and S100A9 are prominently up-regulated in inflammatory diseases being associated with phagocyte activation, like autoimmune and autoinflammatory disorders, infections, allergies, cardiovascular diseases and cancer." (PMID 35055093, 2022). "S100A8 and S100A9 are important proteins in the pathogenesis of allergy." (PMID 32174780, 2020). "We examined the effects of S100A8 and S100A9 in HE subjects with CEL, HES, and reactive eosinophilia-induced allergies." (PMID 32903598, 2020).
anemia (4 papers, 2020 to 2025). A reduction in the number of red blood cells, the amount of hemoglobin, and/or the volume of packed red blood cells. "Additionally, we observed a slower decrease in hemoglobin levels in peripheral blood in the setting of S100a9 knockout in hematopoietic cells, suggesting an amelioration of the MPN phenotype and also fibrosis, which is associated with increasing cytopenias, in particular anemia." (PMID 40823315, 2025). "Characteristics of systemic inflammation are blood leukocytosis, neutrophilia, thrombocytosis, anemia, increased erythrocyte sedimentation rate (ESR), elevated CRP and SAA, and myeloid-related protein 8 and 14 (MRP8/MRP14, also known as S100A8/S100A9)." (PMID 33401496, 2021).
cholesteatoma (4 papers, 2012 to 2024). A pathologic process characterized by the proliferation of keratinizing squamous epithelium resulting in the accumulation of keratin and cells in the middle ear and/or mastoid. "Notably, S100A8 and S100A9 are especially related to the severity of bone destruction caused by cholesteatoma based on Shin staging and Holt staging classification." (PMID 39575241, 2024). "It indicated that the levels of S100A8 and S100A9 were correlated with the severity of EACC based on Shin staging and Holt staging classification, supporting the potential pathogenic factors of S100A8 and S100A9 in cholesteatoma bone erosion." (PMID 39575241, 2024). "Our data indicated the increased S100A8 and S100A9 were associated with increased IFN-γ and TGF-β but decreased IL-10 in clinical and animal models of EACC, consistent with the pathogenesis mechanism of inflammation involved in cholesteatoma pathogenesis." (PMID 39575241, 2024). "The DNA chip analyses indicated that the S100A8 and S100A9 genes might be upregulated and involved in cholesteatoma pathogenesis." (PMID 39575241, 2024). "However, the role of S100A8 and S100A9 and their associated inflammation and other signaling pathways in cholesteatoma have not been investigated yet." (PMID 39575241, 2024). "However, the role of S100A8 and S100A9 and their associated inflammatory and other signaling pathways in cholesteatoma have not been investigated yet." (PMID 39575241, 2024). "TLR4 signalling can also be induced by the DAMPs abundant in cholesteatoma tissue e.g. high-mobility group box 1 proteins (HMGB1), Tenascin, fibronectin, S100A8, S100A9 and also HSP60 and HSP70." (PMID 33627146, 2021). "Real-time PCR of PI3, SPRR1B, LCN2 (lipocalin 2), MMP1, MMP9, MMP10, MMP12, SPP1, GJB2, Bcl-xl (BCL2L1), cIAP2 (BIRC3), S100A7A (koebnerisin), S100A9, SERPINB3, CEACAM6, KRT6B and SERPINB4 revealed that the expression levels of these proteins were higher in cholesteatoma than in external canal skin." (PMID 23285167, 2012).
endometriosis (4 papers, 2021 to 2025). The growth of functional endometrial tissue in anatomic sites outside the uterine body. "As we observed that the magnitude of association increased between S100A9 and endometriosis in bloods collected closer to endometriosis diagnosis, it is plausible that S100A9 contributes to early endometriosis aetiology and pain symptomatology." (PMID 40215752, 2025). "For example, the association between S100A9 levels and endometriosis risk was OR = 1.52 (95%CI = 1.19–1.94) in the overall analysis but the magnitude of association increased to OR = 2.42 (95%CI = 1.17–4.98) when examining those who had blood collected proximal to endometriosis diagnosis." (PMID 40215752, 2025). "Several members of the S100 protein family were under-expressed in the eutopic endometrium of women with endometriosis during the mid-secretory phase: S100A7, S100A8, S100A9, and S100A12." (PMID 35204508, 2022). "Moreover, cyto-hub gene analysis revealed that CSNK2A1, CSNK2A2, TOP1, PRKACA, RBM39 (plasma), ALB, ACTB, GAPDH, FN1, APOA1 (serum), S100-A9, CXCL1, IL1RN, CSTA, S100-A8 (menstrual blood) and THBS1, ALB, CD44, ANXA2, and LUM (urine) were the top 5 proteins expressed in women with endometriosis." (PMID 39061077, 2024).
gout (4 papers, 2013 to 2024). A condition characterized by painful swelling of the joints, which is caused by deposition of urate crystals. "In gout, it`s a key factor that S100A9 drives the production of sodium urate crystals and further induces the secretion of IL-1β in pathogenesis." (PMID 38448514, 2024). "With the criteria of unique peptides ≥ 2, 25 proteins were found highly expressed in gout uniquely, lysozyme C, alpha-1-acid glycoprotein 1, lactotransferrin, protein S100-A9, and myeloperoxidase included." (PMID 35359923, 2022). "Twenty-five proteins were found highly expressed in gout uniquely, lysozyme C and protein S100-A9 included, whose bioinformatic analysis was significantly involved in “neutrophil degranulation” and “prion diseases”." (PMID 35359923, 2022). "The result showed that 25 proteins were found highly expressed in gout uniquely, lysozyme C, alpha-1-acid glycoprotein 1, and protein S100-A9 included." (PMID 35359923, 2022).
head and neck squamous cell carcinoma (4 papers, 2015 to 2025). A squamous cell carcinoma that arises from any of the following anatomic sites: lip and oral cavity, nasal cavity, paranasal sinuses, pharynx, larynx, and salivary glands. "Prior research demonstrated that downregulation of S100A8 and S100A9 was correlated with a decrease in prognosis in inflammatory conditions and cancers involving the oral cavity, such as head and neck squamous cell carcinoma." (PMID 40486046, 2025). "S100A8 is reported to regulate autophagy-dependent ferroptosis in experimental subarachnoid hemorrhage, and S100A9 may also play regulatory roles in ferroptosis but lack “wet” experimental validation in head and neck squamous cell carcinoma." (PMID 37691822, 2023). "However, S100A9 has been reported to be downregulated in head and neck squamous cell carcinoma (HNSCC)." (PMID 26788548, 2015).